KRAS (KRas proto-oncogene, GTPase)
Diseases named in the same sentence as KRAS in open-access papers (continued):
Sharing a sentence is not in itself a finding about the gene and the disease.
tumor (continued). "Additionally, KRAS‐UP signalling was most prominently upregulated in KC2, followed by KC3, suggesting that KC2 tumours might be highly sensitive to G12Ci, whereas KC1 tumours may exhibit resistance." (PMID 41025426, 2025). "By contrast, KRAS tumors lacking these co-alterations more often exhibit inflammatory T-cell infiltration (“immune hot”) and can respond favorably to checkpoint inhibitors, underscoring the interaction between tumor-intrinsic circuitry and antitumor immunity." (PMID 41440526, 2025). "In “negative hyperselected” patients, the absence of resistance-associated mutations (e.g., KRAS, NRAS, BRAF V600E, and EGFR extracellular domain mutations) ensures that the EGFR pathway remains a primary driver of tumor progression, making these tumors more susceptible to EGFR blockade." (PMID 40076838, 2025). "While resistance mechanisms such as elevated KRAS or EGFR activity can lead to emergent drug resistance in some tumours, the primary mode(s) of resistance for many CRC tumours remain unclear." (PMID 41188521, 2025). "However, most investigators have used tumor cell lines and not patient primary tumor cells to validate the killing of tumor target cells by mutant KRAS–specific TCR–transduced T cells in vitro or in vivo." (PMID 39846249, 2025). "Moreover, some details about the site of metastases, the duration of response and molecular profile of the tumour such as KRAS, BRAF were not available in the included studies." (PMID 40133691, 2025). "Furthermore, the implications of this study extend well beyond KRASG12C‐mutant LUAD, challenging the ‘one‐size‐fits‐all’ approach to KRAS‐driven cancers and paving the way for biomarker and TME‐driven combinatorial therapies that address the complex, multifaceted nature of KRAS‐mutant tumours." (PMID 41025426, 2025). "Moreover, a noted trend in KRAS up-regulation was observed in grade (II) and big tumor size, but without showing any significance (p = 0.2, 0.07, respectively)." (PMID 40913040, 2025). "This TCR alongside three other KRAS G12V–reactive TCRs derived from peripheral blood T cells of two healthy donors underwent in vitro testing for specificity, cross-reactivity, functional avidity, function in CD4+ T cells (CD8 coreceptor dependency), and tumor cell-line recognition." (PMID 39484723, 2024). "On a speculative approach, we may suppose that in non-mutated (wild type) KRAS PDAC, EGFR amplification or mutation can be a tumor driver and, therefore, requires a different targeted approach." (PMID 38607041, 2024). "Molecular VAF assays were developed for the quantitative detection of RAS variants at single-nucleotide resolution positive for NRAS, HRAS, and KRAS in tumor tissues but not in the adjacent healthy tissue, which were verified by Sanger sequencing (eFigure 1 in Supplement 1)." (PMID 38758552, 2024). "Except for UTE3, a primary tumor cell line characterized by a low TMB, the other four cell lines all harbored one or two alterations each in genes related to the RAS/MAPK pathway (i.e., the target of avutometinib) including a KRAS G13C alteration in UTE1 and a BRAF D594N alteration in UTE2." (PMID 39240189, 2024). "Further, we speculate YAP1 antagonism may represent a synergistic strategy to sensitize patients with KRAS-driven LUADs lacking STK11 to anti-PD-1 therapy by promoting a “hot” tumor immune microenvironment." (PMID 37968341, 2024). "Another approach involves DC-based vaccines, in which DCs are loaded with KRAS/RAS peptides to prime the immune system against cancer cells, leading to the activation of cytotoxic T cells and memory cells and thereby providing long-term surveillance against tumor recurrence." (PMID 39329742, 2024).
tumor (continued). "However, EREG and AREG overexpression have still been observed across patient tumors regardless of KRAS BRAF mutational status and primary tumor location." (PMID 40727266, 2024). "In the case of KRAS G12C inhibitor therapy, SHP2 inhibition in combination with KRAS G12C inhibition, using SHP099 and ARS-1620, respectively, was shown to confer alterations to the tumour microenvironment and a decrease in MAPK pathway activation, thereby inhibiting tumour growth." (PMID 39372214, 2024). "Moreover, a non-covalent pan-KRAS inhibitor, BI-2865, reduced tumor proliferation in cell lines and mouse models." (PMID 38841166, 2024). "Mechanistically, transcriptomic profiling of LINC00960-depleted cells confirmed its tumor-promoting role, likely through sponging of hsa-miR-34a-5p, hsa-miR-16-5p, and hsa-miR-183-5p, leading to the upregulation of cancer-promoting genes including BMI1, KRAS, and AKT3." (PMID 39039064, 2024). "Competitive behavior promoting tumor development has been well documented in the intestine, where oncogenic mutations in APC, KRAS, or PIK3CA facilitate tumorigenesis through both tumor cell-intrinsic effects on cell growth and non-cell-autonomous effects on neighboring cells." (PMID 37832945, 2024). "Therefore, for precision medicine, older age is a limitation because the proportion of tumours with nonmutated KRAS falls with age." (PMID 38329611, 2024). "In both KRAS wild-type and mutant subgroups, additional factors that could impact EGFR mAb efficacy were explored including the type of chemotherapy, line of therapy, age, sex, tumour sidedness and site of metastasis." (PMID 38402342, 2024). "Therefore, in this research, the proportion of MSI-H, the level of tumor mutational burden, and the expression of programmed death ligand 1 in CRC patients with and without KRAS mutation were analyzed first." (PMID 38292189, 2024). "In three other studies, miR-31 expression was significantly associated with PFS in KRAS wild-type mCRC patients treated with anti-EGFR therapy, but not when the tumour was right-sided, and in these patients, miR-31 was also associated with the time to progression." (PMID 39456841, 2024). "In the CD73-high population, OS benefit was observed in the CD8-high population, PDL1 tumor cell–negative population, and patients with low tumor mutational burden (TMB), KRAS mutations, or without homologous recombination repair mutations when comparing arm A3 with arm A1." (PMID 39106081, 2024). "However, the clinical application of this therapy faces challenges, including the complex tumor microenvironment, a lack of effective biomarkers to identify responsive tumors, and induced resistance to KRAS inhibitors." (PMID 39597944, 2024). "KRAS signaling pathway activation leads to increased cell proliferation, and additional sources of energy substrates are needed to preserve the mitochondrial function of neoplastic cells, especially in the hypoxic and nutrient-deprived PDAC tumor microenvironment." (PMID 37894382, 2023). "Next, to further study the inhibitory effect of ITF2357 on the in vivo growth of Pem-resistant mut-KRAS NSCLC, A549R cells were injected subcutaneously into mice to establish tumor-bearing mice model, and ITF2357 alone or Pem in combination were given to monitor tumor growth." (PMID 36793108, 2023).
tumor (continued). "Intra-tumor heterogeneity was higher in EAS EGFR-mutant-bearing never-smokers than in their EUR equivalents, On the other hand, EUR patients were characterized by more frequent mutations in other driver genes, among them KRAS." (PMID 36817482, 2023). "In xenograft experiments, ARTi-mediated suppression of KRASG12R led to full tumor regression in the absence of KRASG12C, while tumors harboring both oncogenic KRAS alleles only displayed a delay in tumor progression, suggesting that both oncogenes contribute to tumor growth in vivo." (PMID 37552050, 2023). "Live tumor cells treated with anti-KRAS antibody also showed less intense cytoplasmic and less nuclear staining for SOX9, thus providing further evidence that SOX9, a cancer stem cell marker and potential driver in CRC, is a downstream effector of KRAS signaling." (PMID 37051535, 2023). "Tumour heterogeneity may partly explain the reason why some tumours with wild-type KRAS status respond to anti-EGFR therapy while others do not." (PMID 37670299, 2023). "However, Ab3-8 does not inhibit the in vivo growth of tumor xenografts of the HT29 human CRC cells with wild-type KRAS." (PMID 36959802, 2023). "The gene that codes for the KRAS protein is regulated in the 3′UTR promoter region by small non-coding RNAs approximately 20 nucleotides in length, called microRNAs (miRNA), which participate in different processes, such as proliferation, migration, invasion, and tumor development." (PMID 37566020, 2023). "However, the anti-tumor activity of IACS-13909 against KRAS-mutant cancer cells has not yet been established." (PMID 37662925, 2023). "Here, we reveal that SLC25A22, a mitochondrial glutamate carrier, is involved in maintaining an immune repressive microenvironment in KRAS-mutant CRC, and that targeting SLC25A22 could re-activate antitumor immunity and synergize with anti-PD1 to induce tumor regression." (PMID 37542037, 2023). "However, the suppressive effect of 10 mg/kg THZ1 on tumour growth was not significant in mini‐CDX models implanted with SW1990 (KRAS‐G12D) cells (p = .228)." (PMID 38037549, 2023). "Importantly, Liproxstatin-1 treatment of FSP1-overexpressing WT tumors did not result in additional promotion of tumor onset indicating FSP1 to promote KRAS WT tumor initiation by protecting from ferroptosis." (PMID 36443441, 2023). "Preclinical models have also demonstrated that human epidermal growth factor receptor (EGFR) family inhibitors, SHP2 inhibitors, mammalian target of rapamycin (mTOR) inhibitors, and inhibition of CDK4/6 could enhance the anti-tumor activity of MRTX849 and inhibit KRAS-dependent signaling pathways." (PMID 37662925, 2023). "Similarly, for patient BR360026, there was no overlap between plasma variants and tumor NGS; nevertheless, the tumor-agnostic WBC-informed approach revealed a tumor-derived KRAS hotspot mutation that was tracked to determine ctDNA molecular response." (PMID 37814061, 2023). "Moreover, FSP1 expression and its activity in ferroptosis inhibition accelerates tumor onset of KRAS WT cells in the absence of oncogenic KRAS in vivo." (PMID 36443441, 2023). "Moreover, miR-206 is a negative key regulator of oncogenic KRAS-induced NF-κB transcriptional activity, which leads to reduced proangiogenic and proinflammatory factors that further result in tumor growth and poor prognosis." (PMID 38130990, 2023).
tumor (continued). "In the present study, we could not observe any differences in TL within the primary tumour between patients with mutant and wild-type KRAS status, respectively." (PMID 37277368, 2023). "As TRIM58 expression was positively correlated with M2-polarized macrophage and mast cells in KRAS-driven lung adenocarcinoma tumor tissues, which suggested that TRIM58 might facilitate the infiltration of immune cells in tumor microenvironment and enhance antitumor immune reaction." (PMID 36644609, 2023). "One study looking at the impact of changes in substrate stiffness to the behaviour of KRAS-transformed cells showed that cells spread on soft substrates (150 Pa) in an ERK-dependent manner, but not on stiffer substrates (5.7 kPa), closer to those found in fibrotic tumours." (PMID 36175301, 2023). "Taken together, our data establish that endogenous levels of oncogenic KRAS expression render cells more resistant to ferroptosis by upregulating FSP1 through the NRF2 and MAPK pathway allowing for a superior capacity to buffer acute lipid peroxidation during tumor initiation." (PMID 36443441, 2023). "Because most of the KRAS mutant CRCs also have APC mutation, we included both in our study cohorts and classify these cases into HES1 (+) and HES1 (−) groups according to the presence or absence of tumor nuclear expression of HES1." (PMID 37749297, 2023). "For instance, ferroptotic PDAC cells can release KRAS-G12D protein, which drives tumor growth through polarization of macrophages, whereas the release of high mobility group box protein B1 (HMGB1) and membrane proteoglycan decorin (DCN) can stimulate anti-tumor cytotoxic T cell responses." (PMID 37601110, 2023). "However, a pooled analysis of two trials evaluating the combined biomarkers of KRAS, NRAS, BRAF, and PIK3CA showed a significantly reduced benefit from anti-EGFR therapy in patients with any mutant tumor compared with patients with all wt tumors (interaction tests P < 0.05 for PFS, OS, and ORR)." (PMID 37974093, 2023). "PDX models developed represented similar genomic (e.g., ARID1A, PIK3CA, KRAS etc.)and protein (PAX8, ARID1A, napsin A, racemase) profiles to the native patient tumor from which they were derived supporting use of these models as surrogates of the patient tumor." (PMID 37841875, 2023). "Moreover, FSP1 expression alone is sufficient to promote tumor initiation in the absence of oncogenic KRAS by suppressing ferroptosis in vivo." (PMID 36443441, 2023). "However, tumor differentiation, as well as the presence of mutations (EGFR, KRAS, etc.)for adenocarcinoma were not significant predictors for DFS." (PMID 37370781, 2023). "In this group of patients, mutations in IDH2 (n = 3), KRAS (n =3), KIT (n = 3), and SETD2 (n = 1) were identified at low AF (median, 0.86%; range, 0.68 to 2.9%), though the corresponding mutation in the primary tumor was not known." (PMID 35273917, 2022). "We hypothesize that KRAS and BRAF mutations are unlikely to develop within the same lesion given differences in allele frequencies and may reflect tumour heterogeneity detected by the F1L CDx assay." (PMID 35338679, 2022). "This was independent of the KRAS/BRAF mutation status and EGFR expression levels of tumor cells, thus suggesting that resistance mechanisms observed with the therapeutic agents targeting EGFR activity and signaling may not be relevant in this setting." (PMID 36185288, 2022).
tumor (continued). "Interestingly, KRAS mutant and wild-type tumours expressed similar levels of the ligands within each RAG, suggesting an autocrine signalling loop also exists in KRAS mutant tumours in these groups as previously shown." (PMID 36163168, 2022). "In the KRAS-mutant lung cancer model, blockade of both PD-1 and helix-loop-helix transcription factor inhibitor of differentiation 1 knock out significantly enhances the amount of CD8+ T cells as well as the expression of PD-L1, which impairs the tumor growth and increases the survival." (PMID 35582540, 2022). "Together, these findings also support a more generalised model in which activated forms of KRAS or AKT directly and/or indirectly increase levels of YB-1 levels, which, in turn, promote an elevated HIF1α response and potentially other cytoprotective programmes required for tumour formation in vivo." (PMID 34294889, 2022). "Moreover, LY3537982 selectively inhibited the growth of KRASG12C mutant tumor cells but not KRAS wild-type or non-G12C mutant cells." (PMID 35045886, 2022). "Tumor cell immunohistochemical PD-L1, plasma soluble PD-L1 (sPD-L1), TMB/blood TMB (bTMB), mismatch repair defect (dMMR)/microsatellite instability-high (MSI-H), and other biomarkers such as KRAS, STK11, KEAP1, and DNA damage response (DDR) gene variation are potential biomarkers." (PMID 36406130, 2022). "This is significant because previous studies, which demonstrated that tumor site was only significant in wild-type patients, could not prove a true variable effect of KRAS status on PTL." (PMID 35159066, 2022). "This may play an important role in the future development and administration of KRAS inhibitors, especially when tumor tissue is not available." (PMID 36551560, 2022). "Tumor growth is mainly associated with two downstream pathways (MAPK and PI3K), in which activation of PI3K is mediated by not only KRAS but also other upstream signals independent of KRAS." (PMID 36508072, 2022). "In univariate analysis, a high DDR1 immunostaining score was significantly associated with male sex (p = 0.0195), left tumor location (p = 0.0114), BRAF wild-type status (p < 0.0001), KRAS mutated status (p = 0.0041), and absence of expression of the serrated markers Annexin A10 (p = 0.0097)." (PMID 35205677, 2022). "Also, tumor phospho‐ERK1 and phospho‐ERK2 levels were not significantly different between KRAS mutation status (one‐way ANOVA, P > 0.05)." (PMID 34919787, 2022). "Genetic analysis of tumor samples by Next Generation Sequencing (NGS) from treatment resistant patients highlighted that several genetic alterations can contribute to therapy resistance and reduced patient survival e.g. KRAS, STK11, KEAP1 and the phosphatase and tensin homologue (PTEN)." (PMID 35477555, 2022). "Importantly, these non-responder tumor cells are still addicted to KRAS-RAF-MAPK cascade and sensitive to inhibitors targeting the downstream factor ERK." (PMID 35966590, 2022). "In addition, in KRAS-mutant lung adenocarcinoma, STK11/LKB1 inactivation induced immunosuppressive TME and innate resistance to PD-1 inhibitors through downregulation of PD-L1 in tumor cells and effector T-cell exclusion." (PMID 35884355, 2022).